SH2B3 (SH2B adaptor protein 3)
Description:
Links T-cell receptor activation signal to phospholipase C-gamma-1, GRB2 and phosphatidylinositol 3-kinase.
Synonyms: LNK; IDDM20
Tractability: Antibody: its Gene Ontology location is reachable by antibodies, with medium confidence. PROTAC: ubiquitination databases record sites on it.
Gene: Protein-coding gene on chromosome 12 (111,405,000 to 111,451,623, forward strand). Ensembl gene ENSG00000111252.
Subcellular location (Human Protein Atlas): Nucleoplasm
Pathways (Reactome):
Hemostasis: Factors involved in megakaryocyte development and platelet production
Immune System: Negative regulation of FLT3
Signal Transduction: Regulation of KIT signaling
Gene Ontology:
Molecular function: protein binding; protein tyrosine kinase binding; signaling receptor complex adaptor activity; stem cell factor receptor binding; transmembrane receptor protein tyrosine kinase adaptor activity; signaling adaptor activity
Biological process: erythrocyte development; negative regulation of receptor signaling pathway via JAK-STAT; negative regulation of response to cytokine stimulus; thrombopoietin-mediated signaling pathway; cellular response to chemokine; cellular response to interleukin-3; embryonic hemopoiesis; hemopoiesis; intracellular signal transduction; megakaryocyte development; monocyte homeostasis; negative regulation of cell population proliferation; negative regulation of chemokine-mediated signaling pathway; negative regulation of Kit signaling pathway; negative regulation of MAPK cascade; negative regulation of phosphatidylinositol 3-kinase/protein kinase B signal transduction; negative regulation of platelet aggregation; negative regulation of receptor signaling pathway via STAT; neutrophil homeostasis; cell surface receptor protein tyrosine kinase signaling pathway; myeloid cell development; myeloid cell homeostasis; signal transduction
Cellular component: cytosol; plasma membrane
Genetic constraint (gnomAD): Loss-of-function variants: 41 observed, 39.4 expected, observed/expected ratio (o/e) 1.04, 90% interval 0.81 to 1.35. The synonymous counts are far from expectation, so gnomAD's model fits this gene poorly and the ratio says little. Missense variants: 931 observed, 701.73 expected, observed/expected ratio (o/e) 1.33, 90% interval 1.26 to 1.4. Synonymous variants: 383 observed, 311.05 expected, observed/expected ratio (o/e) 1.23, 90% interval 1.13 to 1.34.
Cancer hallmarks: escaping immune response to cancer; angiogenesis (suppresses); suppression of growth (promotes); proliferative signalling (promotes); tumour promoting inflammation (suppresses); escaping immune response to cancer (promotes); genome instability and mutations (promotes); invasion and metastasis (promotes); invasion and metastasis (suppresses); escaping programmed cell death; escaping programmed cell death (suppresses)
Homologues: Orthologues: chimpanzee SH2B3 (99% identical), macaque SH2B3 (97% identical), dog SH2B3 (89% identical), pig SH2B3 (88% identical), guinea pig SH2B3 (77% identical), rat Sh2b3 (72% identical), mouse Sh2b3 (72% identical), tropical clawed frog sh2b3 (53% identical), rabbit SH2B3 (51% identical), zebrafish sh2b3 (39% identical), Drosophila melanogaster Lnk (30% identical). Paralogues in human: SH2B1 (37% identical), SH2B2 (34% identical).
Diseases named in the same sentence as SH2B3 in open-access papers:
SH2B3 is named in the same sentence as 152 diseases in open-access papers, as found by Europe PMC text mining. Sharing a sentence is not in itself a finding about the gene and the disease. The quoted sentences say what the papers report.
Hypertension (34 papers, 2012 to 2025). The presence of chronic increased pressure in the systemic arterial system. "A non-synonymous SNP (rs3184504) in exon 3 of SH2B3 leads to a substitution from arginine to tryptophan in amino acid 262 (R262W), and was associated with hypertension in previous GWAS and in our GWAS analysis." (PMID 39621803, 2024). "Sh2b3 deficient mice also exhibited enhanced T-cell activation with increased IFNγ production in hypertension." (PMID 36951464, 2023). "The Gene Atlas PheWAS database found hundreds of traits in the UK Biobank with the reported sentinel variants of this study and the SH2B3 locus was found to correlate with both hypertension and ischemic heart disease." (PMID 37270590, 2023). "SH2B3 is associated with many autoimmune and cardiovascular disorders, including type 1 diabetes mellitus, celiac disease, myocardial infarction, and hypertension." (PMID 32099610, 2019). "The sentinel variant in the SH2B3 locus (rs7310615) was again found to be highly associated with the presence of hypertension (P=5.9×10−46) and ischemic heart disease (P=4.8×10−14) in the UK Biobank (Table XII in the online-only Data Supplement)." (PMID 31554410, 2019). "Only one missense variant, rs3184504 in SH2B3 gene, was in the intersection of asthma and hypertension GWAS associations." (PMID 31705029, 2019). "A missense SNP (rs3184504) located in an exon of SH2B3 was associated with BP and hypertension in GWAS." (PMID 25882670, 2015). "A missense SNP (rs3184504) located in the third exon of SH2B3 was reported to be associated with BP and hypertension in prior GWAS." (PMID 25882670, 2015). "We previously reported one of the variants associated with retinal venular caliber on chromosome 12q24 near the SH2B3 gene to be associated with coronary artery disease and hypertension." (PMID 23776548, 2013). "Its involvement in blood pressure control and hypertension development was deduced from a genome-wide association, single nucleotide polymorphism in the SH2B3 locus, which encodes for the regulator of cytokine signaling and cell proliferation, and a human longitudinal study." (PMID 41009768, 2025). "The third example is SH2B3 associated with hypertension (PIP = 1)." (PMID 39621803, 2024). "Phenoscanner was used to compare the sentinel variants with other traits from previous GWASs and found that SH2B3 locus for LVEDV was correlated with multiple risk factors which include blood pressure/hypertension, cholesterol/low-density lipoprotein level, diabetes mellitus, and smoking status." (PMID 37270590, 2023). "Interestingly, the SH2B3 locus showed concordant risk effects on several cardiovascular traits, including coronary artery disease and hypertension, but had an opposed effect on LDL cholesterol." (PMID 36369178, 2022). "Several GWAS have implicated SH2B3/LNK gene in hypertension and myocardial infarction." (PMID 34698811, 2021). "However, we observed significant associations linking a kynurenine-modulating missense variant in SH2B3 to a range of diseases including atherosclerosis, hypertension and hypothyroidism, as well as with white blood cell and platelet counts." (PMID 34341450, 2021). "Moreover, a missense mutation of SH2B adaptor protein 3 in immune cells prevents infiltration of leukocytes into the kidneys and high-salt-diet-induced hypertension in the Dahl salt-sensitive rat, further indicating a potential role of immune cells early in the pathogenesis of hypertension." (PMID 32968066, 2020). "This extends prior knowledge of the associations of SH2B324 and B2M25 with hypertension as we demonstrate a unidirectional causal association between SH2B3 expression and plasma B2M levels, and thus provide plausible evidence for a causal role of the SH2B3-B2M axis in hypertension." (PMID 30111768, 2018). "Thus, the pathways implicated in hypertension at the SH2B3 locus may intersect with pathways at the ATP2B1 locus." (PMID 28122634, 2017).
Hypertension (continued). "Our findings are consistent with the role of serum β2M in the incidence and prevalence of hypertension recorded in the Framingham Heart Study and the functionality of the SH2B3-β2M axis for blood pressure homeostasis." (PMID 41009768, 2025). "Leveraging its improved power, FABIO successfully prioritized multiple potentially causal genes associated with the diseases, including GATA3 for asthma, ABCG2 for gout, and SH2B3 for hypertension." (PMID 39621803, 2024). "Given multiple lines of evidence from humans and mice suggesting a key role for SH2B3 to limit BP elevations and end-organ damage in hypertension, SH2B3 represents a potential therapeutic target to modulate T-cell phenotype and hypertension severity." (PMID 36951464, 2023). "Other GWAS on CVDs (e.g., stroke, PAD, hypertension, and acute coronary syndrome (ACS)) have indicated that the SH2B3 locus is a key risk factor for the development of CVDs." (PMID 34943774, 2021). "Integrative network analysis of BP GWAS with mRNA expression profiles from 3679 participants not on anti-hypertensive agents confirms molecular interactions between key drivers such as SH2B3 and hypertension-related genes." (PMID 34698811, 2021). "Previous studies have shown that Rag1−/− and Sh2b3−/− (Sh2b3 plays a suppressive role in the activation of immune responses and cytokine signaling) SS rats were protected from hypertension after having been fed a high-salt diet." (PMID 32179549, 2020). "It is interesting to note that the loss of lymphocyte adaptor protein LNK (also known as SH2B3) exacerbates inflammation and renal and vascular dysfunction following angiotensin II–induced hypertension." (PMID 31321561, 2019). "SH2B3 encodes the lymphocyte adapter protein (LNK), which plays a key role linking inflammation and hypertension, particularly in the kidney and blood vessels." (PMID 29227965, 2017). "In our related paper, we confirmed that deletion of Sh2b3 exacerbates Ang II‐induced hypertension via mechanisms involving inflammation and T‐cell activation." (PMID 25882670, 2015). "Notably, FABIO prioritized multiple candidate genes previously validated for their association with the respective diseases, such as GATA3 for asthma; ABCG2 for gout; and SH2B3 for hypertension." (PMID 39621803, 2024). "Further exploration of the mechanism by which SCFAs mediate Ace2 and Sh2b3 expression may lead to novel avenues for treatment not only of SARS-CoV-2 but a variety of disease states ranging from viral pneumonias to hypertension to stroke." (PMID 35915556, 2022). "In addition, miR-181a-5p was demonstrated to suppress mRNA encoded by hypertension-related ADM and SH2B3 genes." (PMID 35203467, 2022). "Moreover, concordant effects on high blood pressure were found at three loci, including SH2B3, CTF1 and HDAC7, consistent with the epidemiologic association of high blood pressure with increased IgA levels." (PMID 36369178, 2022). "Many genes, whose function may be affected by selected SNPs, have been investigated in the context of BP regulation in vivo, and previous studies linking genetics of hypertension to lymphocyte biology focused on SH2B3 as key driver for hypertension." (PMID 32148083, 2020). "Lastly, as proof‐of‐concept, we investigated the role of one of the top KDs, SH2B3, in relation to hypertension using a Sh2b3−/− mouse model, and tested the genes in the predicted SH2B3 subnetworks for enrichment with differentially expressed genes in the knockout mouse model." (PMID 25882670, 2015). "Our findings therefore demonstrate the utility of our systems biology approach to identify not only candidate genes such as SH2B3 but also gene network‐level mechanism through which the adaptor protein SH2B3 contributes to hypertension through perturbation of inflammatory and T‐cell functions." (PMID 25882670, 2015).
Hypertension (continued). "Interestingly, both SH2B3 and ATXN2 genes have also been associated with cardiovascular alterations, such as myocardial infarction, hypertension, blood pressure and retinal vascular caliber." (PMID 23844121, 2013). "Therefore, elucidating molecular mechanisms where SH2B3 regulating immune cells in hypertension may found novel therapeutic targets for hypertension." (PMID 36703963, 2022). "More recently, the gene SH2B3 (LNK) that encodes SH2B adaptor protein 3 have been confirmed that regulate the immune cell (notably T cells and macrophages) development, differentiation, and signaling in the hypertension according to the genome-wide association studies." (PMID 36703963, 2022). "In addition to the established role of the vasculature, kidneys and central nervous system in pathogenesis of hypertension, low-grade inflammation contributes to this disorder as indicated by experimental models and GWAS studies pointing to SH2B3 immune gene as top key driver of hypertension." (PMID 28360962, 2017). "Emerging data, initially from genetic studies in humans and later refined in animal models, demonstrate an important role for SH2B adapter protein 3 (SH2B3; also known as LNK) in regulating T-cell cytokine production in hypertension." (PMID 36951464, 2023). "Some of these have effects in animal models of hypertension (e.g. SH2B3/LNK, SGK1, and checkpoint inhibitors) while others have not been extensively studied in hypertension specifically, but are predicted to play an important role on the basis of their known effects on T-cell function." (PMID 36951464, 2023).
autoimmune disease (29 papers, 2010 to 2025). A disorder resulting from loss of function or tissue destruction of an organ or multiple organs, arising from humoral or cellular immune responses of the individual to their own tissue constituents. "In keeping with these prior biological observations, our analyses indicated that lead SNP rs3184504-C was associated with lower SH2B3 expression, reduced autoimmune disease (RA and SLE) and higher endometrial cancer risk." (PMID 40428397, 2025). "A missense variant of the LNK/SH2B3 gene is reportedly a risk variant common to several autoimmune diseases, including type 1 diabetes (T1D)." (PMID 41027725, 2025). "According to a previous study, the chromosome 12 SNP (rs3184504) was in the SH2B3 (SH2B adaptor protein 3) gene and is associated with autoimmune disease." (PMID 38373892, 2024). "A specific genetic variation in the LnK/SH2B3 gene, known as a missense variant, has been linked to an increased risk of several autoimmune diseases, including diabetes." (PMID 38482001, 2024). "Variants in SH2B3 have been associated with myeloproliferative neoplasms, idiopathic erythrocytosis, and autoimmune diseases including SLE, rheumatoid arthritis (RA), type 1 diabetes, and multiple sclerosis." (PMID 38417019, 2024). "Although SH2B3 variants have been associated with autoimmune diseases, the cellular mechanisms by which they contribute to autoimmune pathogenesis are yet to be elucidated." (PMID 38417019, 2024). "Mutations in SH2B3 gene have also been associated with autoimmune diseases such as type 1 diabetes mellitus, celiac disease, systemic lupus erythematous, rheumatoid arthritis, and multiple sclerosis." (PMID 37277724, 2023). "Variants in SH2B3 were also described in autoimmune diseases, particularly autoimmune type 1 diabetes." (PMID 36123612, 2022). "We outline the evidence supporting the pathogenic role of SH2B3 p.E395K germline mutation, connecting the dots of association between autoimmune diseases and CMML genesis." (PMID 35281324, 2022). "Germline mutation in SH2B adaptor protein 3 (SH2B3) had been reported before to affect a family with autoimmune disorders and acute lymphoblastic leukemia." (PMID 35281324, 2022). "Although the HLA class I region and SH2B3 have previously been linked with a number of autoimmune diseases, this is the first report of their association with thyroid disease." (PMID 22493691, 2012). "Among them, a missense mutation (R262W) present within the LNK/SH2B3 gene has been reported as a risk variant for several autoimmune diseases, including TID and celiac disease, as well as for cardiovascular disorders such as hypercholesterolemia, myocardial infarction, and hypertension." (PMID 41027725, 2025). "However, the prior association of SH2B3 variants with autoimmune diseases suggests that this association is likely to be confirmed with larger cohorts." (PMID 26652023, 2015). "A similar example occurs with a genetic variant in the SH2B3 gene which may be protective against bacterial infection but which increases susceptibility to celiac disease, an autoimmune disease of the gut resulting from gluten intolerance." (PMID 22577363, 2012). "In addition, polymorphisms of SH2B3 have been associated with skewed haematological parameters and predisposition to autoimmune disease or myeloid malignancy, the most common of these is rs3184504, which results in a R262W substitution that affects PH domain function." (PMID 30816328, 2019). "The strongest pleiotropic locus was the ATXN2/SH2B3, where three SNPs (rs653178, rs4766578 and rs3184504) in near-complete LD (r2=0.99) were tagged as the lead SNPs associated with 10 disease groups/outcomes as a cluster of cardiovascular diseases and autoimmune disorders." (PMID 29437585, 2018). "The role of SH2B3 in autoimmunity is suggested by earlier genome-wide studies in a variety of autoimmune disorders like rheumatoid arthritis, coeliac disease, hepatitis or diabetes type 1." (PMID 40481232, 2025).
autoimmune disease (continued). "Moreover, SH2B3 variants have been reported in extra-hematological pathological conditions; specifically, genome-wide studies have associated somatic SH2B3 polymorphisms with autoimmune diseases, including multiple sclerosis, type 1 diabetes, and systemic lupus erythematosus." (PMID 40481232, 2025). "The results showed that 33.29% (251/754) of the identified pleiotropic genes were shared by at least three diseases, in which SH2B3 was the top pleiotropic gene shared by 12 diseases, implying widespread genetic sharing among autoimmune diseases." (PMID 36869052, 2023). "Occurrence of the SH2B3 missense change was associated with higher T-cell proliferation on PMBCs, stimulated with CD28 and CD3, suggesting a role of altered SH2B3 function in the pathogenesis of autoimmune disorders." (PMID 36123612, 2022). "Two are non-synonymous variants in genes associated with many autoimmune diseases (PTPN22 R620W and SH2B3 (SH2B adaptor protein 3) R262W) and a third is in the HLA class I region." (PMID 22493691, 2012). "Similarly, SH2B3, CD40, and CRP are linked to Sjögren’s syndrome, diabetes mellitus, and celiac disease, reinforcing the genetic connections between RA and other autoimmune diseases." (PMID 40839671, 2025). "Similarly, polymorphisms in the listed genes VAV3, SH2B3, FOXE1 and PTPN22 were identified in the 23andMe database to be associated not only with hypothyroidism but also with other autoimmune diseases." (PMID 38919955, 2024). "Although how SH2B3 mediates autoimmune disease remains unclear, a study provides us with new insights." (PMID 38373892, 2024). "Thus, the GWAS association with AIH inferred that the significance was lower than accepted, and SH2B3 should still be considered for its role in many autoimmune diseases." (PMID 34948375, 2021). "Together, our analysis not only prioritized some new promising drug targets for future drug exploration, but also suggested some known drug targets (NFKB1, SH2B3) that could be exploited for future drug repurposing on autoimmune diseases." (PMID 32879140, 2020). "Data from the current study extend that of previous work identifying that CTLA-4, the IL2_21 region, 6q23 (TNFAIP3), SH2B3, PRKCQ, MMEL1 and now TAGAP are susceptibility loci that are common to the three autoimmune diseases examined in the current study: T1D, CeD and RA." (PMID 20854658, 2010). "Among them, SH2B3, CLEC16A, and TTC34 are mainly involved in immune regulation and autoimmune diseases, while other genes are involved in regulating neurological, adrenal gland, and skeletal muscle-related diseases." (PMID 38943194, 2024). "Among 23 prioritized genes, we found 14 genes with known drug indications on other autoimmune diseases as well as 2 genes (NFKB1, SH2B3) with indications on other diseases." (PMID 32879140, 2020). "Moreover, we predicted potential drug targets for autoimmune diseases, including 2 genes (NFKB1 and SH2B3) with known drug indications on other diseases, highlighting their potential drug repurposing opportunities." (PMID 32879140, 2020).